MST1L (macrophage stimulating 1 like (pseudogene))
Synonyms: BRF-1; D1F15S1A; MST1P9; MSTP9; MSPL7; MSPL-7; MST1P; MST1P7; MSTP7
Gene: Transcribed unprocessed pseudogene on chromosome 1 (16,757,232 to 16,764,480, reverse strand). Ensembl gene ENSG00000186715.
Subcellular location: Secreted
Diseases named in the same sentence as MST1L in open-access papers:
MST1L is named in the same sentence as 10 diseases in open-access papers, as found by Europe PMC text mining. Sharing a sentence is not in itself a finding about the gene and the disease. The quoted sentences say what the papers report.
colitis (1 paper, 2022). Inflammation of the colon. "These candidate biomarkers, MST1L, OLFM4, and DPP10, were predicted to be strongly associated with immune cell infiltration of colitis, especially γδ T cells, neutrophils, and macrophages M1." (PMID 34939750, 2022).
Hepatitis (1 paper, 2020). Inflammation of the liver. "Therefore, more copies of the MST1L gene likely increase its expression in HBV-related ACLF patients, and may further enhance the intensity of hepatitis inflammation." (PMID 33261607, 2020).
ulcerative colitis (1 paper, 2022). An inflammatory bowel disease involving the mucosal surface of the large intestine and rectum. "Furthermore, to examine the model's accuracy in distinguishing between the healthy and ulcerative colitis groups, we further determine the area under the curve (AUC) of MST1L, OLFM4, and DPP10 in GSE48958 and the combined data from GSE36807 and GSE65114." (PMID 34939750, 2022). "Our findings indicated that DPP10, MST1L, DPP10‐AS1, CEP55, ACSL1, MGP, OLFM4, and SGK1 may act as diagnostic biomarkers for ulcerative colitis and that differential immune infiltration cells may help to illustrate the progression of ulcerative colitis." (PMID 34939750, 2022). "AUC was higher than 0.8, indicating that these genes MST1L, OLFM4, and DPP10 are indicators of ulcerative colitis." (PMID 34939750, 2022). "Of these candidate biomarkers, MST1L, OLFM4, and DPP10 were then validated in the GSE48958 dataset and were predicted to be strongly correlated with infiltrating immune cells of ulcerative colitis." (PMID 34939750, 2022). "Correlation between MST1L, OLFM4, and DPP10 in ulcerative colitis and immune infiltration cells." (PMID 34939750, 2022). "Hence, these candidate biomarkers, MST1L, OLFM4, and DPP10, may be involved in the development of ulcerative colitis." (PMID 34939750, 2022).
MST1L also shares sentences with these, for which no sentence is quoted: autoimmune disease (1 paper); diabetes (1); diabetes retinopathy (1); enteritis (1); gestational diabetes (1); nephrogenic diabetes insipidus (1); type 2 diabetes (1).